MGAM (maltase-glucoamylase)
Description:
Alpha-(1,4) exo-glucosidase involved in breakdown of dietary starch oligosaccharides in small intestine. Cleaves the non-reducing alpha-(1,4)-linked glucose residue in linear dextrins with retention of anomeric center stereochemistry. Mainly hydrolyzes short length oligomaltoses having two to seven glucose residues. Can cleave alpha-(1,2), alpha-(1,3) and alpha-(1,6) glycosidic linkages with lower efficiency, whereas beta glycosidic linkages are usually not hydrolyzed.
Synonyms: MGA; MG
Tractability: Small molecule: an approved drug acts on it; a structure with a bound ligand is known; a high-quality ligand is known; it has a high-quality binding pocket; it belongs to a druggable protein family. Antibody: its Gene Ontology location is reachable by antibodies, with high confidence; UniProt places it where antibodies can reach, with medium confidence; UniProt predicts a signal peptide or a membrane-spanning region. PROTAC: a small molecule that binds it is known. Other modalities: an approved drug acts on it.
Target class: Enzyme; Hydrolase
Gene: Protein-coding gene on chromosome 7 (141,907,813 to 142,106,747, forward strand). Ensembl gene ENSG00000257335.
Subcellular location: Apical cell membrane
Pathways (Reactome):
Digestion and absorption: Digestion of dietary carbohydrate
Immune System: Neutrophil degranulation
Gene Ontology:
Molecular function: alpha-1,4-glucosidase activity; oligo-1,6-glucosidase activity; protein binding; catalytic activity; alpha-glucosidase activity; amylase activity; carbohydrate binding; hydrolase activity, hydrolyzing O-glycosyl compounds
Biological process: dextrin catabolic process; maltose catabolic process; starch catabolic process; carbohydrate metabolic process; disaccharide catabolic process
Cellular component: apical plasma membrane; extracellular exosome; ficolin-1-rich granule membrane; plasma membrane; tertiary granule membrane; apical part of cell
Genetic constraint (gnomAD): Loss-of-function variants: 218 observed, 293.06 expected, observed/expected ratio (o/e) 0.74, 90% interval 0.67 to 0.83. The upper end of that interval is the gene's LOEUF score, 0.83, which puts it in group 3 of 6, group 1 being the genes least tolerant of losing a copy. Missense variants: 2,857 observed, 3,117.7 expected, observed/expected ratio (o/e) 0.92, 90% interval 0.89 to 0.94. Synonymous variants: 1,040 observed, 1,111.6 expected, observed/expected ratio (o/e) 0.94, 90% interval 0.89 to 0.99.
Homologues: Orthologues: chimpanzee MGAM (99% identical), chimpanzee MGAM (96% identical), mouse Mgam (80% identical), rat Mgam2 (80% identical), macaque MGAM (65% identical), tropical clawed frog mgam (60% identical), pig MGAM (56% identical), guinea pig MGAM (55% identical), rabbit MGAM (49% identical), Caenorhabditis elegans aagr-2 (13% identical), Caenorhabditis elegans aagr-4 (8% identical), Drosophila melanogaster GCS2alpha (8% identical), and 2 more. Paralogues in human: MGAM2 (44% identical), SI (39% identical), GAA (14% identical), GANAB (9% identical), GANC (9% identical), MYORG (5% identical).
Diseases named in the same sentence as MGAM in open-access papers:
MGAM is named in the same sentence as 61 diseases in open-access papers, as found by Europe PMC text mining. Sharing a sentence is not in itself a finding about the gene and the disease. The quoted sentences say what the papers report.
diabetes (4 papers, 2013 to 2026). "Maltase-glucoamylase inhibitors during the last few years have aroused medical interests in the treatment of diabetes." (PMID 23967118, 2013). "Thus the inhibitor of MGAM is significant for diabetes treatment." (PMID 23967118, 2013).
type 2 diabetes (4 papers, 2018 to 2024). "The potential therapeutic use of polyhydroxylated alkaloids in the treatment of type 2 diabetes due to their ability to inhibit maltase-glucoamylase has been reported." (PMID 36386935, 2022). "MGAM (maltase-glucoamylase) belongs to the glycoside hydrolase family 31 and acts as a target in type II diabetes." (PMID 34384498, 2021). "In this study, the α-glucosidase (maltase-glucoamylase: MGAM) and α-amylase inhibitory properties elicited by xylooligosaccharides (XOSs) prepared from dulse xylan were analysed as a potential mechanism to control postprandial hyperglycaemia for type-2 diabetes prevention and treatment." (PMID 38611816, 2024).
bladder cancer (3 papers, 2020 to 2025). "The distinct N‐glycosylation pattern of MGAM serves as a biomarker for bladder cancer progression." (PMID 40881483, 2025). "Further, we identified distinct N-glycosylation pattern of CD44, MGAM, and GINM1 between NMIBC and MIBC patients, which may be associated with disease progression in bladder cancer." (PMID 32922663, 2020).
breast carcinoma (3 papers, 2021 to 2025). "A higher expression of MGAM has been noted in luminal A breast cancers, and a meta-analysis identified that MCAM mutations are associated with a positive clinical benefit in non-small lung cancer cases." (PMID 34384498, 2021). "have reported that MGAM exhibits a distinct expression pattern in breast cancer among Caucasian and Asian Americans." (PMID 40881483, 2025).
Cirrhosis (3 papers, 2019 to 2023). A chronic disorder of the liver in which liver tissue becomes scarred and is partially replaced by regenerative nodules and fibrotic tissue resulting in loss of liver function. "We found the highest concentrations of MGAM in the urinary exosomes of the patients with cirrhosis and AKI." (PMID 31179128, 2019). "MGAM was shown to be present in exosomes and microparticles in a mouse model of nonalcoholic steatohepatitis (NASH), a common cause of cirrhosis." (PMID 31179128, 2019). "The urine exosome proteomic data from the 4 different groups showed MGAM upregulation in the cirrhosis AKI group to be robust and consistent." (PMID 31179128, 2019). "In AKI patients with cirrhosis, the upregulation of maltase–glucoamylase (MGAM), a renal brush border disaccharidase, in urinary exosomes has also been suggested as a potential biomarker, which may differentiate the type of kidney injury in cirrhosis." (PMID 37510273, 2023). "However, the clinical significance of MGAM upregulation in cirrhosis subjects with AKI needs to be established in future studies." (PMID 31179128, 2019). "In the setting of decompensated cirrhosis, urine exosome protein characterization in AKI patients revealed increased secretion of maltase glucoamylase, a renal brush border disaccharidase." (PMID 32849923, 2020). "Patients with cirrhosis and AKI have upregulation of renal brush border disaccharidase, MGAM, in urinary exosomes which may differentiate the type of kidney injury in cirrhosis; however, the clinical significance of this requires further validation." (PMID 31179128, 2019). "Furthermore, MGAM was increased in patients with cirrhosis but not to the extent as those with AKI." (PMID 31179128, 2019).
depression (3 papers, 2023 to 2025). "MGAM, meanwhile, is involved in biological processes related to oxidative stress and inflammation and has been proposed as a potential diagnostic and prognostic biomarker for patients with pain-depression comorbidity." (PMID 41323994, 2025). "As a result, we discovered 43 key genes associated with pain–depression comorbidity, along with the identification of RNF24, MGAM, FOS, TKT, and SIGLEC5 as hub genes." (PMID 39125922, 2024). "The five hub genes, RNF24, MGAM, FOS, and TKT, were deemed potential diagnostic and prognostic markers for patients with pain–depression comorbidity." (PMID 39125922, 2024). "We found that intestinal microbiota metabolites such as quercetin, equol, and glycocholic acid can affect the course of depression by acting on targets such as MGAM and NR1H4." (PMID 37433869, 2023). "We identified eight signature genes related to both Pueraria and depression, with MMP9, MGAM, and CDK5R1 being of particular importance." (PMID 41323994, 2025). "In the PPI network, DPP4, CYP3A4, EP300 MGAM and NR1H4 showed higher degrees and were identified as essential genes of intestinal microbiota influencing the occurrence of depression through the brain–gut axis." (PMID 37433869, 2023). "In conclusion, the intestinal microbiota can affect the development of depression through the metabolites equol, genistein and quercetin, which act on the critical targets of DPP4, CYP3A4, EP300, MGAM and NR1H4." (PMID 37433869, 2023).
Hyperglycemia (3 papers, 2023 to 2024). An increased concentration of glucose in the blood. "The laminins LAMA2 and LAMB4 are targets in the treatment of ocriplasmin vitreomacular adhesion, whereas the amylases AMY2A and MGAM are targeted by acarbose, voglibose and miglitol for the improvement of postprandial hyperglycemia." (PMID 37684227, 2023). "It was assumed in this study that consumption of dulse could exert antidiabetic potential by the prevention of postprandial hyperglycaemia through the inhibition of carbohydrate digestive enzymes, α-amylase and MGAM, by XOSs." (PMID 38611816, 2024).
prostate carcinoma (3 papers, 2022 to 2025). A carcinoma that arises from epithelial cells of the prostate gland. "In a study focusing on three urogenital cancers and benign prostatic hyperplasia (BPH), researchers discovered a strong association between MGAM glycoproteins and aggressive prostate cancer." (PMID 40881483, 2025). "MGAM exhibited higher expression levels in castration‐resistant prostate cancer metastatic tumors when compared to primary tumors and normal tissue, which is consistence with our study." (PMID 40881483, 2025). "A prognostic model composed of seven protein-coding genes (FOXN4, MGAM, MMP26, ARC, SOX11, PRAME, and VWA5B2) was established, and it was strongly associated with biochemical recurrence following radical prostatectomy in prostate cancer." (PMID 37255653, 2022).
colitis (2 papers, 2021 to 2026). Inflammation of the colon. "Reduced MGAM activity increases intestinal fermentation substrates and elevates short-chain fatty acid (SCFA) levels, playing a critical role in colitis, while monocytes and macrophages are also regulated by SCFAs." (PMID 41526548, 2026).
colorectal cancer (2 papers, 2018 to 2025). A primary or metastatic malignant neoplasm that affects the colon or rectum. "This study investigates MGAM as a potential direct target of alpha‐glucosidase inhibitors in colorectal cancer (CRC), explores its biomarker potential, and evaluates gene expression patterns across diverse cancers." (PMID 40881483, 2025). "MGAM is found down-regulated and considered as a candidate serum biomarker in colorectal cancer." (PMID 29439675, 2018).
gastric cancer (2 papers, 2013 to 2025). A primary or metastatic malignant neoplasm involving the stomach. "The genome‐wide analysis conducted using complementary DNA microarray has revealed that MGAM is among the genes exhibiting decreased expression in intestinal‐type gastric cancer, suggesting its involvement in carcinogenesis." (PMID 40881483, 2025). "In gastric cancers, MGAM is among the most aberrantly expressed mRNAs, with decreased expression observed in intestinal‐type gastric cancer." (PMID 40881483, 2025). "ADAM9 has been previously implicated as a potential oncogene and therapeutic target for various cancers whilst MGAM gene has been reported to be amplified in gastric cancer genomes." (PMID 23405089, 2013). "Similarly, the MGAM gene has been reported to be amplified in gastric cancer." (PMID 23405089, 2013).
Insulin resistance (2 papers, 2021 to 2022). Increased resistance towards insulin, that is, diminished effectiveness of insulin in reducing blood glucose levels. "MGAM has become an efficient drug target for insulin resistance." (PMID 34527658, 2021).
kidney injury (2 papers, 2019 to 2021). Trauma to the kidney. "The proteomic data showed a higher concentration of MGAM in the urine exosomes of decompensated cirrhotic patients, with and without kidney injury (groups 2 and 3)." (PMID 31179128, 2019).
lung adenocarcinoma (2 papers, 2018 to 2025). A carcinoma that arises from the lung and is characterized by the presence of malignant glandular epithelial cells. "Additionally, MGAM is a significantly mutated gene in lung adenocarcinoma." (PMID 29439675, 2018).
atherosclerosis (1 paper, 2026). A disease characterized by the build-up of fatty material and calcium deposition in the arterial wall resulting in partial or complete occlusion of the arterial lumen. "As an intestinal a-glucosidase, accumulating evidence indicates that gut microbiota dysbiosis is a core driver of cardiometabolic risk factors such as atherosclerosis, suggesting that MGAM may indirectly influence AMI through the "gut-heart axis"." (PMID 41526548, 2026).
autism (1 paper, 2014). Persistent deficits in social interaction and communication and interaction as well as a markedly restricted repertoire of activity and interest as well as repetitive patterns of behavior. "MGAM is a gene involved in starch metabolism, with dysregulated mRNA expression in autism." (PMID 24988487, 2014).
Brugada syndrome (1 paper, 2023). A genetically heterogeneous condition characterized by complete or incomplete right bundle branch block accompanied by ST elevation in leads V1-V3. "At least seven genes putatively mapped by our significant non-reference TEs have been already associated with schizophrenia: LRRC4C, LRRC7, ST8SIA4, MGAM, ADAMTS1, MIR548AJ2 and SCN5A, which is also linked to the Brugada syndrome." (PMID 37244930, 2023).
cutaneous melanoma (1 paper, 2025). A primary melanoma arising from atypical melanocytes in the skin. "SNV mutations in the MGAM gene are more prominently expressed in the glycolytic subtype of cutaneous melanoma (SKCM), which is associated with the poorest prognosis compared to other subtypes." (PMID 40881483, 2025).
herpesvirus infections (1 paper, 2023). "All shared putative protein biomarkers tended to predict infection in the same direction for both pathogens, except MGAM, which was elevated in herpesvirus infections but reduced in hemoplasma infections." (PMID 38193073, 2023).
hyperlipidemia (1 paper, 2021). "Similarly, ESR1(ERα), MAOA, MGAM, PTK2, MMP1, GNB5, PIK3R3, and other targets had higher degree values, suggesting that these genes might be the core targets of PCE intervention in hyperlipidemia." (PMID 34925692, 2021).
intestinal tuberculosis (1 paper, 2021). A tuberculosis that involves the intestine. "Finally, the measurement of MGAM levels in a variety of inflammatory diseases such as ulcerative colitis and intestinal tuberculosis could be worthwhile." (PMID 34040049, 2021).
irritable bowel syndrome (1 paper, 2023). Irritable bowel syndrome (IBS) is a chronic functional condition of the lower gastrointestinal (GI) tract characterized by abdominal pain or discomfort and disordered bowel habit (diarrhea, constipation, or fluctuation between the two). "What is the influence of potential SI and MGAM interaction on their individual trafficking behavior and in functional gastrointestinal disorders (FGID), such as irritable bowel syndrome and in CSID?" (PMID 36968271, 2023).
sucrase-isomaltase deficiency (1 paper, 2023). "In gastrointestinal disorders, such as congenital sucrase-isomaltase deficiency (CSID), when SI activities are reduced or absent, MGAM can act in an auxiliary mode partially substituting for the abolished SI function." (PMID 36968271, 2023).
tumor (8 papers, 2013 to 2025). "Our comprehensive analysis using the GCSA database revealed intricate relationships between MGAM and its paralog with cancer‐related pathways across various tumor types." (PMID 40881483, 2025). "Mutations in MGAM have been linked to enhanced response rates, increased PD‐L1 expression, and higher TMB levels in NSCLC patients, suggesting a potential role in modulating tumor‐infiltrating immune cells." (PMID 40881483, 2025). "Furthermore, they offer valuable insights into the possible pathways through which MGAM might influence tumor development." (PMID 40881483, 2025).
cancer (4 papers, 2013 to 2025). A tumor composed of atypical neoplastic, often pleomorphic cells that invade other tissues. "Subsequently, we will expand our analysis to a broad spectrum of human cancers to identify patterns of MGAM expression, mutations, copy number variations (CNVs), methylation status, immune cell infiltration, and associated drugs across various malignancies." (PMID 40881483, 2025). "Analysis of MGAM mutations showed a high mutation rate across various cancers, including SKCM, UCEC, LUSC, LUAD, HNSC, COAD, BRCA, and STAD." (PMID 40881483, 2025). "The association of MGAM with cancers linked to carbohydrate metabolism pathways underscores the importance of metabolic reprogramming in cancer." (PMID 40881483, 2025). "Our goal is to determine whether MGAM could serve as a pan‐cancer therapeutic target based on observed expression/mutation patterns across different cancer types." (PMID 40881483, 2025). "MGAM exhibited frequent mutations and aberrant methylation in several cancers." (PMID 40881483, 2025). "Following this, we delved into the implicated gene pathways and protein–protein interactions, assessing MGAM's and its paralog MGAM2's potential as a prognostic and diagnostic marker in cancer." (PMID 40881483, 2025). "To enrich our comprehension of MGAM's function, we broadened our research to encompass its lesser‐known variant, MGAM2, scrutinizing its differential expression across various forms of cancer." (PMID 40881483, 2025). "We explored the differential expression of MGAM across various cancers, employing R software and online databases." (PMID 40881483, 2025). "The expression of MGAM and its correlation with various drugs were investigated using data from the Cancer Therapeutics Response Portal (CTRP) and GDSC databases." (PMID 40881483, 2025). "Future research with functional studies should aim to integrate MGAM expression data with other molecular markers to develop more comprehensive predictive models for cancer therapy." (PMID 40881483, 2025). "This research endeavors to explore the potential of MGAM as a therapeutic agent in cancer treatment through a multifaceted approach." (PMID 40881483, 2025). "Several studies were conducted on the importance of MGAM in cancer: The significance of the MGAM gene in various types of cancer has been extensively explored through network pharmacology and molecular docking technologies." (PMID 40881483, 2025). "The GSCA database also predicted a significant association between MGAM, MGAM2, and various cancer‐related pathways." (PMID 40881483, 2025). "The implications of our findings highlight the potential of MGAM as a significant biomarker for assessing cancer prognosis." (PMID 40881483, 2025). "ROC curve analysis was conducted to assess the diagnostic efficacy of MGAM and MGAM2 in various cancers." (PMID 40881483, 2025). "As our understanding deepens through continuous research and the identification of specific genetic variants like rs2960746, the potential of MGAM and MGAM2 in revolutionizing cancer care becomes even more apparent." (PMID 40881483, 2025). "The relationship between MGAM expression and methylation further complicates the gene's role in cancer progression, highlighting the need for comprehensive epigenetic analyses." (PMID 40881483, 2025). "Therefore, to gain a clearer understanding of the role and potential significance of MGAM in the molecular mechanisms underlying cancer, with the ultimate goal of identifying a target for drug repurposing strategies in cancer treatment, we conducted a comprehensive pan‐cancer analysis of MGAM." (PMID 40881483, 2025). "Whereas our study focuses on CRC, the widespread involvement of MGAM in various cancer types suggests its crucial role in cancer biology." (PMID 40881483, 2025). "The top 10 frequently affected cancer-associated genes are HIRA (OG), CSMD1 (TS), CDH13 (TS), PRRX1 (OG), FHIT (TS), MGAM (OG), TBL1XR1 (OG), RHOA (OG), FGF14 (TS), and CNTNAP2 (TS)." (PMID 35013466, 2022).